BMAL1 (basic helix-loop-helix ARNT like 1)
Diseases named in the same sentence as BMAL1 in open-access papers (continued):
Sharing a sentence is not in itself a finding about the gene and the disease.
breast carcinoma (continued). "The increased expression of MMP9, orchestrated by BMAL1, enhances the invasive potential of breast cancer cells, contributing to their ability to invade and metastasize." (PMID 38361941, 2024). "Using either a BMAL1-Luc reporter or time-course western-blot of clock factors, we also observed variable clock function among established breast cancer cell lines representing various tumor subtypes." (PMID 38319971, 2024). "Knockdown of BMAL1 disrupts circadian rhythm and enhances migration or invasion in lung cancer, breast cancer, and glioma cells." (PMID 38189049, 2023). "Tumor hypoxia-induced acidosis decreases the transcription activation and protein stability of BMAL1 to promote breast cancer metastasis in vitro." (PMID 33752691, 2021). "Studies have found that mutations in BMAL1, CRY1, and CRY2 are often associated with a higher risk and recurrence of acute myeloid leukemia and endometrial, ovarian, colorectal, and breast cancers." (PMID 34149816, 2021). "BMAL1 was significantly decreased in breast cancer compared with normal breast tissue in GSE5364 and GSE3744." (PMID 32316196, 2020). "These treatments provide a novel mechanism for inhibiting breast cancer metastasis by maintaining circadian gene BMAL1 in tumor hypoxia-induced acidosis." (PMID 32316196, 2020). "As a result, expression of BMAL1 and CLOCK was associated with poor prognoses in breast cancer patients." (PMID 32316196, 2020). "We then investigated the possible clinical relevance of BMAL1 expression between normal and breast cancer tissues using the GSE database." (PMID 32316196, 2020). "Remarkably, acidosis-mediated metastasis was significantly alleviated by BMAL1 overexpression in breast cancer cells." (PMID 32316196, 2020). "We found that BMAL1 was reduced in tumor hypoxia-induced acidosis, and recovered by selectively targeting acidic pH in breast cancer cell lines." (PMID 32316196, 2020). "Together, these results suggest that tumor acidosis-mediated decrease of the BMAL1 promotes tumor metastatic potency in breast cancer cell lines, and selectively targeting tumor acidosis to maintain BMAL1 prevents breast cancer metastasis." (PMID 32316196, 2020). "In this study, we focused this phenomenon more on breast cancer and we aimed to determine the new pathway for decreasing BMAL1 and recovering reduced BMAL1 in the breast cancer microenvironment." (PMID 32316196, 2020). "We used MDA-MB-231 and TUBO-P2J breast cancer cell lines, which have metastatic potencies, to investigate the relationship between reduced BMAL1 by acidosis and breast cancer metastasis." (PMID 32316196, 2020). "Since yellowish medium indicates that acidosis has occurred and in the previous study, the BMAL1 was disrupted under hypoxia-induced acidosis in osteosarcoma cells, we expected that hypoxia-induced acidosis also reduced BMAL1 expression in breast cancer cells." (PMID 32316196, 2020). "In summary, we showed that tumor hypoxia-induced acidosis reduced the BMAL1 circadian clock gene in breast cancer." (PMID 32316196, 2020). "Our results suggest that the hypoxia-induced acidosis reduced BMAL1 independently of HIF-1α in breast cancer cells." (PMID 32316196, 2020). "These databases predicted that breast cancer involves hypoxia-induced acidosis, which reduces BMAL1 and CLOCK." (PMID 32316196, 2020). "In particular, knocked-out BMAL1 significantly promoted tumor metastasis in MDA-MB-231 breast cancer cells." (PMID 32316196, 2020). "To characterize the role of BMAL1 in acidosis-mediated breast cancer metastasis, we used an overexpression system to maintain BMAL1 expression levels during acidosis." (PMID 32316196, 2020). "Together, these results suggested that BMAL1 was reduced by chronic hypoxia independently of HIF-1α in breast cancer cells." (PMID 32316196, 2020).
breast carcinoma (continued). "Our analysis indicates that five SNPs, BMAL1 rs2279287, CLOCK rs12505266, CRY2 rs10838524, PER1 rs2735611, PER2 rs934945, are significantly associated with the breast cancer risk in the Polish association study." (PMID 31739444, 2019). "This study confirmed a new mechanism by which BMAL1 up-regulated MMP9 expression to increase breast cancer metastasis, to provide research support for the prevention and treatment of breast cancer." (PMID 31346317, 2019). "In this study, we demonstrated that BMAL1 can promote the invasion and metastasis of breast cancer cells, and at least partially up-regulate the expression of MMP9." (PMID 31346317, 2019). "In order to explore the role of BMAL1 in the occurrence and development of breast cancer, therefore, we selected breast cancer cell lines containing MCF7, T47D, MDA-MB-231 and ZR-75-30 cells." (PMID 31346317, 2019). "Fourth, In addition to MMP9, in the breast cancer cells, BMAL1 also up-regulated the expression of TNF-a, IL8, and uPA at the mRNA level, which are all target genes of NF-κB, suggesting a potential role of BMAL1 in NF-κB/MMP9 pathway." (PMID 31346317, 2019). "Then, we studied the effect of BMAL1 on the proliferation and invasion ability of breast cancer by overexpressing BMAL1 through MTT, clonal formation, Scratch wound healing and Transwell migration assays." (PMID 31346317, 2019). "The women who had one or more protective alleles (derived at least one gene BMAL1 rs2279287 and/or PER1 rs3027178) had a significantly reduced breast cancer risk." (PMID 31739444, 2019). "In the present study, we used an invasive breast cancer cell line, MDA-MB-231, to analyse the effect of BMAL1 mutation on invasion." (PMID 30375470, 2018). "As an extension of the influences of CLOCK and Bmal1 on cancer development, the CLOCK/BMAL1 heterodimer has been shown to regulate cell-cycle genes that are involved in breast cancer progression." (PMID 26220712, 2015). "After applying FPRP and BFDP in women with at least four night shifts, an increased risk of breast cancer was associated with variant alleles of SNPs in the genes AANAT (rs3760138, rs4238989), BMAL1 (rs2290035, rs2278749, rs969485) and ROR-b (rs3750420)." (PMID 23822714, 2013). "Women with the highest number of successive night shifts and carrying at least one variant allele of SNPs in the two core circadian genes BMAL1 (rs2290035, rs969485) and ROR-b (rs3903529, rs3750420) had a noteworthy increased risk of breast cancer." (PMID 23822714, 2013). "In the main effects analysis, two SNPs in BMAL1 and CLOCK were associated with risk of breast cancer." (PMID 23822714, 2013). "In the subjects with three night shifts, SNPs in BMAL1 (rs2278749), BMAL2 (rs2306074), CSNK1E (rs5757037), NPAS2 (rs17024926), PER3 (rs1012477) and MTNR1A (rs131113549) were associated with decreased breast cancer risk." (PMID 23822714, 2013). "Critically, through functional validation, we have identified for the first time that BMAL1 is a key downstream effector molecule mediating melatonin-induced reprogramming of breast cancer cell glucose metabolism (manifested as glycolytic inhibition) and consequently inhibiting tumor cell growth." (PMID 41228459, 2025). "Prior research indicates that BMAL1 may modulate the proliferative potential of breast cancer cells through the regulation of glycolytic processes." (PMID 41228459, 2025). "This suggests BMAL1 may influence the biological behaviour of breast cancer by regulating the glycolytic pathway and exhibits a negative correlation with glycolysis." (PMID 41228459, 2025). "Additionally, previous data analysis showed that the core molecule BMAL1 is expressed in various breast cancer cell lines, including TNBC." (PMID 41228459, 2025). "Given that BMAL1 may represent a downstream target of melatonin, this study further investigated the regulatory effects of BMAL1 overexpression on the biological behaviour of breast cancer cells." (PMID 41228459, 2025).
breast carcinoma (continued). "To investigate whether silencing BMAL1 can reverse the decrease in breast cancer cell viability and clonogenicity induced by melatonin treatment in vitro, we conducted relevant experiments." (PMID 41228459, 2025). "Conversely, Bmal1 contributes to breast cancer progression by elevating MMP9 expression." (PMID 37923872, 2024). "Further supporting these findings, lung cancer cells incubated with conditioned media from BMAL1-deficient CAMs showed augmented NLRP3 inflammasome activation, driving cancer cell proliferation, consisting to the effects that observed in breast cancer with BMAL1 knockdown." (PMID 38607733, 2024). "Interestingly, on the contrary, BMAL1 overexpression promotes invasion and metastasis of breast cancer cells by upregulation matrix metalloproteinase 9 (MMP9), a mediator of local tumor invasion and distant metastasis." (PMID 38189049, 2023). "Moreover, much evidence has identified BMAL1 as a key element in metastasis in breast cancer and glioblastoma." (PMID 36768253, 2023). "Similar to the role of CLOCK in suppressing stemness-related malignancy in breast cancer, recent transcriptomic and cell-based studies from Nuri Ozturk’s group have shown that BMAL1 disruption enhances EMT gene expression and the invasive properties of malignant breast cancer cells." (PMID 36430659, 2022). "Additionally, altered circadian rhythms have been reported to be correlated with the prognosis of breast cancer.The exist circadian rhythm and the core circadian gene Bmal1, persist in malignancy breast cancer cells." (PMID 33752691, 2021). "Hypoxia significantly reduces BMAL1 protein expression in MCF-7, T47D (luminal A), ZR-75-1 (luminal B), MDA-MB-231, MDA-MB-468, Hs578T (basal-like) human breast cancer, and TUBO and TUBO-P2J (TUBO metastatic variant) mouse breast cancer cells." (PMID 32316196, 2020). "We hypothesized that hypoxia-mediated secretory factors reduce BMAL1 expression in breast cancer cells." (PMID 32316196, 2020). "Therefore, we suggested that in breast cancer cells, a hypoxia-mediated decrease of BMAL1 protein expression is pH dependent and HIF-1 α independent." (PMID 32316196, 2020). "We therefore suggest that tumor hypoxia-induced acidosis promotes metastatic potency by decreasing BMAL1, and that tumor acidosis could be a target for preventing breast cancer metastasis by sustaining BMAL1." (PMID 32316196, 2020). "Together, these results showed that hypoxia-induced acidosis reduced BMAL1 expression, which could be prevented by selectively targeting the acidic pH in breast cancer cells." (PMID 32316196, 2020). "In this study, we investigated the BMAL1 may take a crucial effect in the progression of breast cancer cells." (PMID 31346317, 2019). "In this study, we identified that BMAL1 promoted the invasion and metastasis of breast cancer cells through regulating the expression of MMP9, and the possible underlying mechanism is mainly recruiting CBP to increase the acetylation level of p65, further activate the NF-κB signaling pathway." (PMID 31346317, 2019). "The carriers who had at least one variant allele of BMAL1 rs2279297 (p = 0.05) or were a recessive homozygote of CRY2 rs3824872 (p = 0.0004), had a significantly decreased gene expression level in breast cancer tissue compared to the women with a dominant homozygous genotype." (PMID 31739444, 2019). "First, in breast cancer cells, BMAL1 promotes migration and invasion." (PMID 31346317, 2019). "Among the differentially methylated genes was hypermethylation of the promoter for miR-219, a miRNA that has been linked to breast cancer development and has been identified as a potential regulator of circadian duration via the modulation of CLOCK- and BMAL1-dependent Per transcription." (PMID 26220712, 2015).
breast carcinoma (continued). "The carriers of variant TT genotype of SNP rs2278749 in the BMAL1 gene with an OR of 0.45 (95% CI, 0.23- 0.90) and the homozygote genotype TT of rs3749474 in the CLOCK gene with an OR of 0.64 (95% CI, 0.45- 0.92) had reduced risk of breast cancer." (PMID 23822714, 2013). "BMAL1 may be an important mediating mechanism of melatonin regulating breast cancer." (PMID 41228459, 2025). "However, there was also a study indicating that BMAL1 could promote breast cancer cell invasion and metastasis by up-regulating MMP9 expression through the activation of the NF-κB signaling pathway." (PMID 40046513, 2025). "However, in colon cancer and breast cancer, BMAL1 appears to play an oncogenic function." (PMID 40638681, 2025). "Therefore, from the perspective of cellular senescence, reduced expression of BMAL1 in breast cancer may weaken antisenescence defense mechanisms, making cancer cells more prone to accumulating DNA damage and promoting cancer progression." (PMID 40046513, 2025). "Several studies have shown that brain and muscle aryl hydrocarbon receptor nuclear translocator-like 1 (BMAL1), an important molecule for maintaining circadian rhythms, inhibits the growth and metastasis of tumor cells in several types of cancer, including lung, colon, and breast cancer." (PMID 32231148, 2020). "However, in breast cancer, the relationship between the circadian gene BMAL1 and the tumor microenvironment is still largely unknown, and it is insufficient to explain only mTOR signaling pathway." (PMID 32316196, 2020). "Induction of BMAL1 expression may provide a strategy for suppression of breast cancer metastasis." (PMID 31346317, 2019). "Finally, we demonstrated that BMAL1 could promote the invasiveness of breast cancer cells by up-regulating the expression and activity of MMP9." (PMID 31346317, 2019). "In a study of nurses with breast cancer, exposure to night work was associated with increased methylation of the CLOCK, BMAL1, PER1 and CRY1 genes, compared with controls, suggesting that epigenetic regulation of these clock genes may have a role in breast cancers linked to shift workers." (PMID 33089179, 2019). "In addition to MMP9, BMAL1 also up-regulated the downstream target genes of NF-κB in breast cancer cells, such as TNF, IL8, uPA, and luciferase reporter gene showed that BMAL1 could activate the activity of NF-κB reporter gene." (PMID 31346317, 2019). "Disrupted expression of core circadian genes (BMAL1, CLOCK and PER3) and hub genes such as ACTB, GAPDH and CDK1 suggests that circadian gene dysregulation promotes breast cancer progression and represents a potential therapeutic target." (PMID 41908013, 2025). "They report a similar downregulation of PER1, PER2, CRY2, and HLF, in breast cancer samples while CLOCK, ARNTL(BMAL1), and BHLHE40 levels remained relatively unchanged." (PMID 38319971, 2024). "In a breast cancer mouse model, CLOCK and BMAL1 in the TME promoted tumorigenesis and metastasis through the upregulation of WNT10A-mediated ALDH3A1 expression in cancer stem cells." (PMID 37524704, 2023). "In fact, the expression of certain specific circadian genes (BMAL1, PER2, and TIMELESS) has been demonstrated to be disrupted in breast cancer cell lines." (PMID 36012374, 2022). "When MCF-7 and MDA-MB-231 breast cancer cells were exposed to hypoxic conditioned media (HCM), BMAL1 was reduced." (PMID 32316196, 2020). "The role of clock proteins (e.g., Per2 and BMAL1) has been recently proposed in DOX-induced cell death and breast cancer." (PMID 31973180, 2020). "Cycloheximide (CHX), an inhibitor of de novo protein synthesis, decreased the half-life of BMAL1 protein expression in MCF-7 and MDA-MB-231 breast cancer cells." (PMID 32316196, 2020). "Together, these results show that melatonin maintained BMAL1 expression by inhibiting the expression of LDH-A to prevent hypoxia-induced acidosis in MCF-7 and MDA-MB-231 breast cancer cells." (PMID 32316196, 2020).
breast carcinoma (continued). "When breast cancer was divided into BMAL1 and LDH-A low or high groups by the mean median value, recurrence free survival (RFS) was higher in the BMAL1 high group than the BMAL1 low group and lower in the LDH-A high group than the LDH-A low group." (PMID 32316196, 2020). "Cancer cells and primary breast cancer tissues were immunostained for the measurement of circadian clock proteins (CLOCK, BMAL1 and PER1) and acetylserotonin methyltransferase (ASMT)." (PMID 33194597, 2020). "By contrast, when BMAL1 was knocked down using small interfering RNA, tumor migration was significantly promoted in MDA-MB-231 and TUBO-P2J breast cancer cell lines." (PMID 32316196, 2020). "BMAL1 mainly affects the expression of MMP9, which promoting the invasion and metastasis of breast cancer." (PMID 31346317, 2019). "The expressions of BMAL1 and MMP9 were also examined in different human breast cancer cell lines, showing that the expression of BMAL1 was higher in more invasive breast cancer cells and was positively correlated with the expression of MMP9." (PMID 31346317, 2019). "Relatively higher expression of BMAL1 was identified in MDA-MB-231 cells than in T47D and ZR-75-30 cells, consistent with the expression of MMP9 in breast cancer cells." (PMID 31346317, 2019). "BMAL1 and CLOCK, as key transcription factors, are integral to breast cancer progression." (PMID 39139571, 2024). "Under hypoxia and acidic conditions, while the protein level of BMAL1 was almost reduced, the mRNA level was not completely reduced in breast cancer cells." (PMID 32316196, 2020). "In addition, the protein and mRNA levels of BMAL1 in MCF-7 and MDA-MB-231 breast cancer cells were reduced in chronic hypoxia but unchanged when the pH of the medium was neutralized by NaOH or buffered by NaHCO3." (PMID 32316196, 2020). "Additionally, we found that knock-down of CLOCK promotes metastasis, and double knock-down of BMAL1 and CLOCK further promotes metastasis in MDA-MB-231 breast cancer cells." (PMID 32316196, 2020). "Importantly, increased migration by acidosis was alleviated in the green fluorescent protein (GFP)-tagged BMAL1-transfected MDA-MB-231 and TUBO-P2J breast cancer cells because GFP-BMAL1 was overexpressed despite decrease of endogenous BMAL1 by acidosis." (PMID 32316196, 2020). "In our study, we identified the promoting effect of BMAL1 on MMP9 transcription, which may provide a novel mechanism for human breast cancer invasion and metastasis." (PMID 31346317, 2019). "Our findings of consistent reduction of Bmal1 mRNA levels, together with reports from others of altered PER proteins, confirms that the intrinsic feedback machinery regulating clock expression is disrupted in early breast cancer." (PMID 30348208, 2018). "The results showed that silencing BMAL1 reduced cell apoptosis; further observations via colony formation assays and CCK-8 assays revealed that it could restore the proliferative capacity of breast cancer cells." (PMID 41228459, 2025). "Interestingly, orthotopic transplantation of E0771 breast cancer cells depleted for BMAL1 revealed that BMAL1 functions as a tumor suppressor in obese, but not in lean mice." (PMID 33987528, 2021). "However, in breast cancer cells, we found that the hypoxia-mimetic agent CoCl2 did not affect BMAL1 protein expression." (PMID 32316196, 2020). "However, recent studies have shown that circadian protein BMAL1 has a cancer-promoting effect in breast cancer, but the specific molecular mechanism is not well understood." (PMID 31346317, 2019). "In this study, it was found that overexpression of BMAL1 could promote the invasion and metastasis of breast cancer cells, but could not affect the proliferation of breast cancer cells." (PMID 31346317, 2019).